H2BP2 (H2B histone pseudogene 2)
Synonyms: formerly HIST2H2BB
Gene: Transcribed unprocessed pseudogene on chromosome 1 (143,904,223 to 143,904,603, reverse strand). Ensembl gene ENSG00000234571.
Diseases named in the same sentence as H2BP2 in open-access papers:
H2BP2 is named in the same sentence as 1 disease in open-access papers, as found by Europe PMC text mining. Sharing a sentence is not in itself a finding about the gene and the disease.
H2BP2 shares sentences with these, for which no sentence is quoted: myopathy (1 paper).